PRM2 (protamine 2)
Diseases named in the same sentence as PRM2 in open-access papers (continued):
Sharing a sentence is not in itself a finding about the gene and the disease.
nephritis (1 paper, 2015). Inflammation of renal tissue. "The antibodies against PRM1 and PRM2 were detected in the sera from SLE patients with and without nephritis, although these positive signals were weak." (PMID 26098692, 2015).
testicular germ cell tumor (1 paper, 2023). A germ cell tumor arising from the testis. "Three of them (PRM2, FSCN3 and TEKT2) were significantly down-regulated in the testicular germ cell tumors and their methylation levels were associated with the pathogenesis." (PMID 37891374, 2023).
ZIKV infection (1 paper, 2018). "In the testes, ZIKV infection led to approximately a 50% decrease in PRM2+ round and elongating spermatids." (PMID 30070988, 2018).
cancer (2 papers, 2021 to 2024). A tumor composed of atypical neoplastic, often pleomorphic cells that invade other tissues. "Two antigens (n = 2/50, PLEKHA8 and PRM2) showed abundant uniform reactivity across all healthy, all benign and virtually all cancer samples (n = 78/80, n = 79/80 respectively) and were excluded from subsequent analyses." (PMID 34681879, 2021). "cg27326750 is a methylation probe located within the PRM2 protein-coding gene, which has not been linked with cancer yet." (PMID 38612473, 2024).
infection (1 paper, 2023). The state of being infected such as from the introduction of a foreign agent such as serum, vaccine, antigenic substance or organism. "Germ cell markers (PLZF for spermatogonia, PGK2 for spermatocytes, and PRM2 for spermatids) were not significantly modified by the infection at any time points." (PMID 37830818, 2023).
PRM2 also shares sentences with these, for which no sentence is quoted: oligospermia (2 papers); Obesity (1); Sertoli Cell-Only Syndrome (1); testicular tumors (1); toxoplasmosis (1); tumor (1).